INS (insulin)
Diseases named in the same sentence as INS in open-access papers (continued):
Sharing a sentence is not in itself a finding about the gene and the disease.
cancer (continued). "Cancer cells can produce the IGFs, so while insulin must travel through circulation to reach a tumor, IGFs have the potential to interact with a cancer cell via autocrine, paracrine, and endocrine mechanisms." (PMID 26029167, 2015). "Recently, IGF/insulin is proposed to play roles in the maintenance of cancer cell stemness as well as cancer metabolism." (PMID 26074875, 2015). "Twenty-three (2.6%) target genes for miR-203a are involved in insulin signaling pathway (P = 6.72 × 10−13), 25 (2.9%) in focal adhesion (P = 2.01 × 10−11), and 31 (3.6%) in cancer-related pathways (P = 3.51 × 10−11)." (PMID 25700309, 2015). "There is epidemiological data to suggest that insulin secretion rate and insulin-like growth factor 1 (IGFI) levels influence cancer risk and/or cancer progression." (PMID 25961014, 2015). "IGF-II acting through the IR-A promotes cancer cell proliferation, survival, and migration by activating some unique signaling molecules compared to those activated by insulin." (PMID 26217307, 2015). "For example, hsa-miR-602 was identified to be functionally involved in MAPK, insulin, and calcium signaling pathways, whereas has-miR-205 3p was found to be involved in cancer, MAPK, Wnt and cell adhesion signaling pathways." (PMID 25955790, 2015). "This was especially noted for growth-promoting pathways including the Insulin, mTOR, ErbB, Wnt, MAPK, and VEGF signaling pathways, and various cancer-associated pathways." (PMID 25960543, 2015). "Epidemiological evidence supporting an association between disruption in insulin/IGF1 homeostasis and cancer mortality is strong, but complicated by multiple confoundment." (PMID 26284118, 2015). "The first and second modules were enriched with genes from the insulin signaling pathway and adipocytokine signaling pathway, and the third module was enriched with genes involved in cancer related pathways." (PMID 26083494, 2015). "Genetic and pharmacological manipulation clearly shows important roles of IGF/insulin and their receptors not only in cultured cancer cells but also in mouse tumor models." (PMID 26074875, 2015). "Further studies are needed to assess the long-term effect of TDZs and DPP-4 inhibitors on glycemic control in HCV patients, and the effects of insulin and SU on cancer progression." (PMID 26441826, 2015). "Metformin can also exert its anti-tumor activity through insulin-independent direct actions on cancer cells." (PMID 26111812, 2015). "Because of the recognized role of the insulin/IGF system in cancer, in the last decade, this system has been seriously considered as a therapeutic target." (PMID 25798130, 2015). "Many cancer cell lines express insulin and/or IGF1 and/or hybrid receptors, and depend on insulin/IGF1 for in vitro growth." (PMID 26284118, 2015). "Epidemiological evidence linking the insulin/IGF system with cancer has been reinforced by a large body of pre-clinical work in cell culture and animal models that has established many of the mechanisms underlying these associations." (PMID 26029167, 2015). "The reason is considered to be the low sales in Japan of injection medicines for outpatients’ use of injections at home, such as those for insulin, growth hormones, and pain-killers for cancer." (PMID 26234979, 2015). "Ames dwarf mice are also highly insulin sensitive and have improved glucose tolerance, enhanced memory and learning skills as they age and are protected from cancer." (PMID 26176567, 2015). "Increased energy balance, which culminates in increased adiposity, changes the levels of hormones such as insulin, adiponectin, leptin and IGF-1, which is also associated with cancer including ovarian." (PMID 25895126, 2015).
cancer (continued). "DM and cancer share several common mechanisms, including increased insulin and insulin-like growth factor (IGF) signaling, dysregulation of ovarian steroid hormones, and chronic inflammation." (PMID 25866823, 2015). "We aimed at defining common pathways across many of our regions and found that the pathways representing numerous (7 or 8) regions were ‘serum’ (rank #7), ‘insulin’ (#8), ‘matrix’ (#10), ‘carcinoma’ (#13) and ‘complement’ (#16)." (PMID 26225558, 2015). "Over-activation of IGF/IGF-1R and insulin/IR signaling pathway has been reported to promote several cancer hallmarks, including uncontrolled cell proliferation, migration, transformation, metastasis, angiogenesis and glycolysis." (PMID 24970814, 2014). "Surprisingly, among all the 277 KEGG pathways, a large number of DEGs are distributed in “pathways in cancer”, “insulin signaling”, and “MAPK signaling pathway”, which rank on the top 3, 9, and 15 KEGG pathways containing 49, 35, and 32 DEGs, respectively." (PMID 24606580, 2014). "High circulating levels of insulin and IGF-1 have been established as risk and prognostic factors for many cancers." (PMID 25026276, 2014). "The E. multilocularis metacestode larval stage displays a marked organ-tropism towards the mammalian host’s liver where it grows infiltratively, like a malignant tumour, and where the highest concentrations of insulin within the mammalian body can be found." (PMID 24468049, 2014). "Using Illumina-Solexa sequencing to analyze DEGs in the PSG, here we found that many Ras1-induced genes are distributed in “pathways in cancer”, “insulin signaling”, and “MAPK signaling pathway”." (PMID 24606580, 2014). "Disease severity at insulin initiation was further evaluated by treatment intensity level, which proved to be an important predictor of cancer mortality." (PMID 24667573, 2014). "Based on a number of preclinical and clinical studies, the mechanisms of metformin in different cancer cells have been proposed to be both insulin-dependent (systemic/indirect effects) and insulin-independent (local/direct effects)." (PMID 24887156, 2014). "IGF-1, a well-known pathway with an affinity for insulin, is also critical to cell proliferation and apoptosis and has been shown to be related to various types of cancer, such as breast and colon." (PMID 24927125, 2014). "The cross-reaction of insulin with IGF receptors on cancer cell membranes increases the S-phase fraction in tumors, increasing the cells susceptibility to the cytotoxicity of anticancer drugs." (PMID 24885964, 2014). "This opens the possibility that the IR-A holds an important position in the stimulation of cancer cell proliferation in response to insulin and insulin analogs." (PMID 24904529, 2014). "Since high glucose and high insulin can induce cancer cell proliferation through different mechanisms, controlling blood glucose levels and insulin levels at the appropriate level would be beneficial in cancer patients bearing DM." (PMID 24864247, 2014). "In the context of cancer, insulin signaling and thus the role of leptin in the regulation of pancreatic β-cell functions are of importance." (PMID 24587106, 2014). "Decreased ATGL activity exerts beneficial effects such as improved glucose tolerance and insulin sensitivity and protection from cancer-induced cachexia." (PMID 25258314, 2014). "KEGG pathway analysis indicated that those genes were implicated in 113 pathways, including “Pathways in cancer”, “MAPK signaling”, “Endocytosis”, “Insulin signaling” and “Wnt signaling”." (PMID 24520312, 2014). "Recent studies showed that insulin promote cancer progression by enhancing metabolic capacities of cancer cells." (PMID 24864247, 2014). "IGF-1 and insulin increased the proportion of cells with metabolically active mitochondria (cell viability) of stromal and cancer cells by between 13 and 55% (HMEC-1 in high glucose with insulin and WiDr in high glucose with IGF-1, respectively)." (PMID 24396438, 2014).
cancer (continued). "As primary outcome, we found 54 incident cancer cases occurring after the new use of insulin in intent-to-treat analysis." (PMID 25329887, 2014). "The connection of insulin with cancer occurrence can be further confirmed by data obtained on vanadium." (PMID 25580464, 2014). "Why then enzymes of differentiated cells, hepatocytes or adipocytes, respond preferentially to catabolic hormones; as if, in cancer, differentiated cells, were relatively insensitive to insulin signals." (PMID 25247026, 2014). "Currently, potential connections between impaired glucose and insulin levels and cancer diseases are investigated." (PMID 25580464, 2014). "Therfore, insulin predominantly targets cancer cells, with a relative sparing of host normal tissues." (PMID 24885964, 2014). "In the present study we show that insulin reduced the 11beta-HSD2 activity in cancer colon cell lines (HCT116, SW620 and HT-29) at the transcriptional level, in a time and dose dependent manner." (PMID 25133511, 2014). "Second, 5 DEGs were observed in both “pathways in cancer” and “insulin signaling pathway”, including pi3kl, pi3ks, cbl1, cbl2, and cbl3." (PMID 24606580, 2014). "Coupled with its role in inhibiting the protein synthesis in cancer cells, controlling gluconeogenesis and glucose uptake and influencing insulin/ IGF-1 levels and signaling, makes it an attractive contender mediating the antitumor effects of CR." (PMID 25026276, 2014). "Glyceollin I has many bioactivities including anti-bacterial, anti-nematode, anti-fungal, anti-estrogenic and anti-cancer, anti-oxidant, anti-inflammatory, insulin sensitivity enhancing, and vascular contraction attenuation properties." (PMID 24399048, 2014). "Several miRNAs with evident roles in cancer are reported to participate in insulin and ROS signaling pathways." (PMID 24895527, 2014). "Many GPCRs and their cognate agonists also mediate autocrine/paracrine growth stimulation in a variety of cancer cells and dramatically synergize with insulin/IGF-1 in inducing mitogenic signaling." (PMID 25295009, 2014). "On the other hand, insulin is known to promote proliferation and resistance to apoptosis of cancer cells." (PMID 24752580, 2014). "Recent studies have demonstrated that metformin exhibits antiproliferative effect in cancer cells both directly as well as indirectly by improving insulin sensitivity, and consequently decreasing hyperinsulinaemia." (PMID 24858012, 2014). "Reduction of inflammatory signaling, improvement of insulin sensitivity, or counteracting the hypoxia-inducible factors appears to be relevant pathways in prevention of cancer development and reducing its progression." (PMID 24829560, 2014). "First, we detected the common DEGs annotated in “pathways in cancer”, “insulin signaling pathway”, and “MAPK signaling pathway” by qPCR." (PMID 24606580, 2014). "Second, we detected the individual DEGs annotated in “pathways in cancer”, “insulin signaling pathway”, and “MAPK signaling pathway” by qPCR." (PMID 24606580, 2014). "For pi3ks, cbl2, and cbl3, the three DEGs presented in both “pathways in cancer” and “insulin signaling pathway”, LY294002 and rapamycin showed the strongest and weakest inhibitory effects, respectively." (PMID 24606580, 2014). "Short-term studies indicate that CR in humans lowers fasting insulin, core body temperature, and DNA damage and possibly decreases cancers." (PMID 24883306, 2014). "Instead, we observe a substantial shift in the human transcriptome towards ad libitum-fed mice across all the tissues and functional pathways examined, including insulin signaling, cancer and immune pathways." (PMID 24400080, 2014). "The cumulative dose assessment of exposure to glargine insulin revealed a modest protective effect for cancer mortality (SHR 0.94, 95% CI 0.89–0.99, p = 0.033)." (PMID 24667573, 2014).
cancer (continued). "This is beneficial to new mitotic stem cells, which respond to both insulin and catabolic hormones, and rewire their metabolic pathways in a “cancer mode”." (PMID 25247026, 2014). "FDG-PET studies in cancer patients on a KD confirmed that CHO restriction with subsequent insulin inhibition and ketosis inhibits tumor glycolysis in vivo." (PMID 24436017, 2014). "For example, miR-602 is putatively involved in regulating MAPK and insulin signaling pathways; however, miR-1290 is involved in cancer, focal adhesion, and insulin signaling pathways." (PMID 25299961, 2014). "In order to increase the biological plausibility of the timeframe between insulin exposure and cancer event, a separate analysis was performed using the cumulative time and dose exposure up to one year before cancer event or end of follow-up." (PMID 24667573, 2014). "It is known that glucose metabolism is vital for both normal and cancer cells and that insulin can stimulate glucose uptake by GLUTs." (PMID 24887156, 2014). "In the present investigation, 4-NQO produced significantly higher serum insulin levels among the cancer control animals which were reversed after treatment with combination of telmisartan with cisplatin and not with cisplatin alone." (PMID 24381940, 2013). "Adiponectin, being the most abundant adipokine, is particularly interesting because it enhances insulin sensitivity, and its circulating levels are inversely related to cancer occurrence and cancer stage." (PMID 24073332, 2013). "MiR-9 has been shown to be of importance during the immune response, post-traumatic stress, neuronal differentiation, different forms of cancers and exocytosis of insulin from pancreatic islets." (PMID 23525285, 2013). "With the exception of its role in cancer, miR-375 is also a significant regulator in mammalian pancreatic islet-cell development and in the regulation of insulin secretion, thus indicating its diverse role in normal physiology." (PMID 24137444, 2013). "Although many factors have been postulated to mediate effects of obesity on cancer, recent research has focused on insulin as a potentially relevant mediator." (PMID 24391834, 2013). "Insulin is known to promote cellular growth and proliferation, and receptors for insulin are highly expressed on various types of cancer cells." (PMID 24282613, 2013). "A crucial role is supposed to be played by the altered insulin signalling, occurring in obese patients, which fuels cancer cell growth, proliferation and survival." (PMID 23497533, 2013). "KEGG pathway analysis revealed that the common genes expressed in FGF2 and IL-11 are enriched for cell adhesion, tight junction, insulin signaling and cancer pathways." (PMID 24194720, 2013). "The proliferative effects of insulin are believed to be an indirect effect through increasing levels of bioavailable IGF-1, and the role of IGF-1 as a risk factor for cancer has been well established." (PMID 23819063, 2013). "The increase in deaths from cancer was more obvious among insulin-treated women, among whom mortality increased especially with regard to cancer of digestive organs, breast and urinary tract, and lymphoid tissue and blood." (PMID 23837500, 2013). "Regarding possible mechanisms responsible for cancer prevention, regular physical activity helps maintain a healthy body weight, regulates sex hormones, insulin, and prostaglandins and has various beneficial effects on the immune system." (PMID 24073332, 2013). "The risks of overall mortality (adjusted RR = 1.89, 95% CI 1.47–2.43, P<0.0001) and death from cancer (adjusted RR = 2.16, 95% CI 1.39–3.35, P = 0.001) were all significantly higher in the insulin users than in the non-insulin users." (PMID 23308218, 2013). "Insulin-induced changes in PKM2 status directly resulted in amplification of cancer-metabolism-specific parameters like glucose uptake, lactate production, glycolytic pooling and macromolecular synthesis." (PMID 23837608, 2013).
cancer (continued). "As a consequence of this excess of type A isoform receptors, insulin can favor cancer progression and facilitate the neoplastic growth of tumors that remain clinically irrelevant." (PMID 29147337, 2013). "Considering the PKM2-mediated pro-cancerous effects of insulin, our results seemingly provide a mechanistic understanding into insulin’s role in cancer metabolism." (PMID 23837608, 2013). "Further investigation is needed concerning the increased cancer mortality among insulin-treated diabetic individuals." (PMID 23837500, 2013). "We show that insulin promotes cancer metabolism by upregulating PKM2 expression and decreasing its activity." (PMID 23837608, 2013). "We observed 98 cancer events with an incidence rate of 76.8 per 10,000 patients per year in the insulin users and 170 cancer events with an incidence rate of 74.3 per 10,000 patients per year in the non-insulin users." (PMID 23308218, 2013). "Due to the rarity of such adverse events, it would take much larger exposure to evaluate any potential additive relationship on cancer risk between GLP-1 RAs and insulin." (PMID 23061470, 2013). "Both findings point towards higher insulin sensitivity, in the case of IGFBP-2 also towards a reduced cancer risk." (PMID 24236134, 2013). "Amongst diabetic populations, metformin has the lowest cancer mortality profile when compared to sulphonylurea or insulin treatment, in a dose and duration of treatment-dependent manner." (PMID 23573093, 2013). "The study identifies new PKM2-mediated effects of insulin on cancer metabolism, thus, advancing the understanding of insulin’s role in cancer." (PMID 23837608, 2013). "Signalling by the insulin pathway is highly relevant in cancer development as both extracellular-signal-regulated kinase (ERK) and phosphatidylinositol-3 kinase (PI-3 K) pathways are triggered by activation of the insulin receptor (IR)." (PMID 24073332, 2013). "Apart from insulin, other glucose-lowering therapies have been involved in the relationship between type 2 diabetes and cancer." (PMID 24278227, 2013). "Evidences in recent years have suggested a crucial role of insulin in cancer cell growth and survival." (PMID 23837608, 2013). "The significant pathways included Wnt signaling pathway, transcriptional misregulation in cancer and, insulin signaling pathways." (PMID 23741487, 2013). "Apparently, dual regulation of PKM2 expression and activity by insulin ensures the promotion of both aerobic glycolysis and anabolic synthesis, required for cancer cell proliferation." (PMID 23837608, 2013). "The current analysis suggests that when C-peptide, HOMA-IR, serum glucose and HbA1c are considered simultaneously, markers of insulin secretion (C-peptide) appear to be the major determinant for future cancer mortality but only in women." (PMID 23405181, 2013). "In vitro and in vivo studies showed increased peripheral insulin sensitivity and cancer growth inhibition by Ampk activation." (PMID 23620761, 2013). "These methods are then applied to a case-cohort study designed to evaluate the associations of insulin and insulin-like growth factor (IGF)-axis protein levels with the development of cancer in postmenopausal women." (PMID 23834739, 2013). "Cancer control rats were found to exhibit significant (P < 0.05) increased serum insulin levels as compared to normal control group." (PMID 24381940, 2013). "Our results contribute to better understanding of the role of insulin in cancer metabolism and thus cancer progression." (PMID 23837608, 2013). "Over-expression of IR-A is in fact emerging as a feature of cancer cells where it mediates cell survival, proliferation, and migration under insulin and IGF-2 stimulus." (PMID 24391834, 2013). "The anti-diabetic drug metformin is a stereotypical DR mimetic that exerts its anti-cancer activity through a dual mechanism involving insulin-related (systemic) and mTOR-related (cell-autonomous) effects." (PMID 23986086, 2013).